PDHA1 (pyruvate dehydrogenase E1 subunit alpha 1)
Description:
Together with PDHB forms the heterotetrameric E1 subunit of the pyruvate dehydrogenase (PDH) complex. The PDH complex catalyzes the overall conversion of pyruvate to acetyl-CoA and CO(2), and thereby links cytoplasmic glycolysis and the mitochondrial tricarboxylic acid (TCA) cycle. It contains multiple copies of three enzymatic components: pyruvate dehydrogenase (E1), dihydrolipoamide acetyltransferase (E2) and dihydrolipoamide dehydrogenase (E3) (Probable). The E1 subunit catalyzes both the thiamine pyrophosphate (TPP)-dependent decarboxylation of pyruvate and the reductive acetylation of a lipoyl group covalently linked to the lipoyl-bearing domains of E2.
Synonyms: PHE1A; E1alpha; PDHA; PDHAD; PDHCE1A
Tractability: Small molecule: a structure with a bound ligand is known; it has a binding pocket of medium quality. PROTAC: ubiquitination databases record sites on it; its protein half-life has been measured.
Target class: Enzyme; Oxidoreductase
Gene: Protein-coding gene on chromosome X (19,343,893 to 19,361,718, forward strand). Ensembl gene ENSG00000131828.
Subcellular location: Mitochondrion matrix
Subcellular location (Human Protein Atlas): Mitochondria
Pathways (Reactome):
Metabolism: PDH complex synthesizes acetyl-CoA from PYR; Regulation of pyruvate dehydrogenase (PDH) complex
Metabolism of proteins: Mitochondrial protein degradation
Signal Transduction: Signaling by Retinoic Acid
Gene Ontology:
Molecular function: protein binding; pyruvate dehydrogenase (acetyl-transferring) activity; oxidoreductase activity, acting on the aldehyde or oxo group of donors, disulfide as acceptor
Biological process: pyruvate decarboxylation to acetyl-CoA
Cellular component: mitochondrion; nucleus; pyruvate dehydrogenase complex; mitochondrial matrix; protein-containing complex
Gene-disease validity (ClinGen):
ClinGen rates the evidence that PDHA1 causes each of these diseases.
Leigh syndrome (X-linked): Definitive. A progressive neurological disease defined by specific neuropathological features associating brainstem and basal ganglia lesions.
mitochondrial disease (X-linked): Definitive.
Homologues: Orthologues: chimpanzee PDHA1 (100% identical), macaque PDHA1 (100% identical), rabbit PDHA1 (99% identical), guinea pig Pdha1 (99% identical), dog PDHA1 (98% identical), rat Pdha1 (98% identical), mouse Pdha1 (98% identical), pig PDHA1 (98% identical), tropical clawed frog pdha1 (84% identical), zebrafish pdha1a (81% identical), zebrafish pdha1b (79% identical), Caenorhabditis elegans pdha-1 (59% identical), and 2 more. Paralogues in human: PDHA2 (85% identical), BCKDHA (28% identical).
Diseases named in the same sentence as PDHA1 in open-access papers:
PDHA1 is named in the same sentence as 163 diseases in open-access papers, as found by Europe PMC text mining. Sharing a sentence is not in itself a finding about the gene and the disease. The quoted sentences say what the papers report.
breast carcinoma (24 papers, 2015 to 2025). "It was shown that the expression of the following CRGs—CDKN2A, PDHA1, and lipoyltransferase 1 (LIPT1)—was associated with breast cancer incidence." (PMID 38732186, 2024). "PDHA1 has been reported to be an independent prognostic biomarker and a potential target for breast cancer immunotherapy." (PMID 39867656, 2024). "Previous studies have shown a significant downregulation of PDHA1 expression in breast cancer, ovarian carcinoma, and gastric cancer resulting in enhanced glycolysis and an association with poor prognosis." (PMID 37741973, 2023). "In our current study, we comprehensively analyzed the expression profile and stage characteristics of these CRGs in breast cancer, finding that CDKN2A, PDHA1 and LIPT1 expression were associated with pathological stage of BC." (PMID 36518756, 2022). "Our data show that HBXIP promotes the glucose metabolism reprogramming through downregulating SCO2 and PDHA1 in breast cancer cells, involving HIF1α/miR-183/96/182 cluster/pVHL signaling." (PMID 26309161, 2015). "Accordingly, we validated that HBXIP was able to downregulate the expression levels of SCO2 and PDHA1 in breast cancer cells." (PMID 26309161, 2015). "Our data showed that miR-183/96/182 cluster was able to downregulate the expression of SCO2 and PDHA1 in breast cancer cells at the post-transcriptional level." (PMID 26309161, 2015). "Overall, we conclude that HBXIP regulates the glucose metabolism reprogramming and downregulates SCO2 and PDHA1 in breast cancer." (PMID 26309161, 2015). "The downregulation of SCO2 and PDHA1 leads to the increase of lactate production and intracellular glucose, and the decrease of ROS, promoting the growth of breast cancer cells." (PMID 26309161, 2015). "Next, we try to identify the mechanism by which HBXIP downregulates SCO2 and PDHA1 in breast cancer cells." (PMID 26309161, 2015). "It was also shown that PDHA1 overexpression was significantly associated with a negative prognosis in patients with breast cancer due to low overall survival (OS) and low recurrence-free survival (RFS) rates." (PMID 38732186, 2024). "The study uncovers that PDHA1 could act as an autonomous prognostic biomarker and a promising target for immunotherapeutic approaches in breast cancer." (PMID 39867656, 2024). "Notably, PDHA1 expression levels in breast cancer tissue are lower than in normal breast tissue, and its expression has been associated with breast cancer prognosis." (PMID 39702350, 2024). "Furthermore, immune infiltration analysis of CRGs revealed that PDHA1 expression is significantly associated with the infiltration levels of CD4+ memory T cells, M0 and M1 macrophages, and mast cells in breast cancer." (PMID 39867656, 2024). "Oncoprotein HBXIP enhances glucose metabolism reprogramming by inhibiting PDHA1 in breast cancer." (PMID 36699089, 2022). "When PDHA1 is downmodulated in breast cancer, the oncoprotein hepatitis B X-interacting protein may help to drive glucose metabolic remodeling." (PMID 36046242, 2022). "Thus, we conclude that the oncoprotein HBXIP enhances glucose metabolism reprogramming through suppressing SCO2 and PDHA1 in breast cancer." (PMID 26309161, 2015). "Therefore, we conclude that miR-183/96/182 cluster is able to downregulate the expression of SCO2 and PDHA1 at the post-transcriptional level in breast cancer cells." (PMID 26309161, 2015). "It suggests that the miR-183/96/182 cluster might be involved in the glucose metabolism reprogramming through targeting SCO2 and PDHA1 in breast cancer cells." (PMID 26309161, 2015). "As cuproptosis-promoting genes, FDX1, LIAS, LIPT1, DLD, DLAT, and PDHA1 were under-expressed in breast cancer; at the same time, CDKN2A, which inhibited cuproptosis, was over-expressed in breast cancer, suggesting that cuproptosis might involve in the protective mechanism of BRCA." (PMID 39432636, 2024). "In addition, elevated PDHA1 expression correlated with poorer outcomes in breast cancer patients." (PMID 39867656, 2024).
breast carcinoma (continued). "In summary, this study suggests that the herbal recipe SLC has the potential to act as an agent for inhibiting OXPHOS through the PDK1/PDHA1 and SIRT1/PGC-1α/NRF1/TFAM signaling axis to treat HER2-positive breast cancer." (PMID 41465397, 2025). "Overall, SLC influences oxidative phosphorylation via the PDK1/PDHA1 and SIRT1/PGC-1α/NRF1/TFAM signaling pathways and downregulates the HER2 pathway, thereby ultimately inhibiting HER2-positive breast cancer progression." (PMID 41465397, 2025). "In the GSE145548 cohort, the downregulation of ATF2 in MCF7 breast cancer cells resulted in substantial changes in the expression of cuproptosis regulators (DLST, GCSH, PDHA1, LIPT1, and DLD)." (PMID 39867656, 2024). "The univariate Cox regression demonstrated that LIPT1, PDHA1, and DLAT as predictor to poor survival and further classified breast cancer samples into three geneClusters (geneClusterA, geneClusterB and geneClusterC)." (PMID 37353799, 2023). "Multiomics approaches were used to create a cuproptosis-related signature with six genes (DKN2A, MTF1, PDHA1, DLD, LIPT1, and FDX1) for breast cancer." (PMID 36312586, 2022). "Prognosis analysis revealed poor OS and RFS rates in breast cancer patients with elevated levels of CDKN2A and PDHA1 and low levels of MTF1, DLD, LIPT1, and FDX1." (PMID 36312586, 2022). "We then constructed a cuproptosis-related signature with six genes (DKN2A, MTF1, PDHA1, DLD, LIPT1, and FDX1) for breast cancer, which predicted the OS rate with an accuracy that ranged from medium to high." (PMID 36312586, 2022). "A recent study suggested that PDHA1, a subunit of the PDH complex, helped breast cancer cells adapt to metabolic and oxidative stresses." (PMID 36567939, 2022). "In conclusion, multiomics approaches were conducted to develop a cuproptosis-related signature with six genes (DKN2A, MTF1, PDHA1, DLD, LIPT1, and FDX1) for breast cancer." (PMID 36312586, 2022). "In the GSE145548 cohort, knockdown of ATF2 in breast cancer cells MCF7 resulted in the dramatic change of cuproptosis regulators (DLST, GCSH, PDHA1, LIPT1 and DLD)." (PMID 36733399, 2022). "qPCR results showed that two model lncRNAs (USP2-AS1, NIFK-AS1) and three Cuproptosis genes (FDX1, PDHA1, DLAT) expressed differently between 10 pairs of breast cancer tissue samples and adjacent samples." (PMID 36699089, 2022). "In breast cancer, HBXIP can enhance glucose metabolism reprogramming through suppressing SCO2 and PDHA1." (PMID 28388957, 2017). "Based on the notion that miR-183/96/182 cluster inhibited the expression of SCO2 and PDHA1 through targeting SCO2 and PDHA1 mRNA CDSs, we further evaluated the effect of miR-183/96/182 on the glucose metabolism reprogramming in breast cancer cells." (PMID 26309161, 2015). "Furthermore, the oncoprotein Hepatitis B X-interacting protein (HBXIP) has been found to enhance glucose metabolic reprogramming in breast cancer by inhibiting cytochrome C oxidase (SCO2) and PDHA1." (PMID 39702350, 2024). "FDX1 (P < 1E‐12), LIAS (P = 2.22E‐16), LIPT1 (P < 1E‐12), DLD (P < 5.46E‐09), DLAT (P = 3.14E‐02), PDHA1 (P = 1.15E‐07), MTF1 (P = 1.07E‐09), and GLS (P = 2.48E‐05) were downregulated in breast cancer, while PDHB (P = 5.04E‐07) and CDKN2A (P = 1.62E‐12) were upregulated." (PMID 39432636, 2024). "Though the function of PDHA1 in PCa has not been reported, it can impact the occurrence of many cancers such as ovarian cancer, gastric cancer, and breast cancer by influencing glucose metabolism." (PMID 37711156, 2023). "FDX1, PDHA1 and DLAT also significantly down regulated in breast cancer." (PMID 36699089, 2022). "Another vital discovery of our research was that we developed a cuproptosis-related prognostic signature containing six genes (CDKN2A, MTF1, PDHA1, DLD, LIPT1, and FDX1) for breast cancer, which predicted the OS rate with an accuracy that ranged from medium to high." (PMID 36312586, 2022).
breast carcinoma (continued). "Additionally, it was discovered via research of the impact of gene expression patterns on overall survival in breast cancer that those expressing high levels of ATP7A, DBT, DLAT, DLD, GLS, PDHA1, and SLC31A1 had a bad prognosis." (PMID 36059516, 2022). "Thus, we conclude that HBXIP promotes the growth of breast cancer cells through miR-183/96/182 targeting SCO2 and PDHA1 in vivo." (PMID 26309161, 2015). "According to above observation that HBXIP downregulates SCO2 and PDHA1 which are targeted by miR-183/96/182, we are interested in whether HBXIP is able to upregulate miR-183/96/182 in breast cancer cells." (PMID 26309161, 2015).
prostate carcinoma (21 papers, 2017 to 2026). A carcinoma that arises from epithelial cells of the prostate gland. "Decreased PDHA1 expression was associated with poor overall survival of individuals with oesophageal squamous cell carcinoma, prostate cancer, ovarian carcinoma, and GC." (PMID 36895378, 2023). "PDHA1 gene deletion in prostate cancer cells causes metabolic remodeling, with the cells becoming more glutamine-reliant." (PMID 36046242, 2022). "In this study, anoikis resistance (AnoR) prostate cancer cells exhibited a substantial increase in PDHA1 expression, which enhanced their survival and metastatic potential by increasing resistance to ferroptosis." (PMID 41724793, 2026). "Previous studies have shown that PDHA1 is able to achieve consistent prostate cancer development in human xenograft tumor models by affecting lipid synthesis." (PMID 36967449, 2023). "GLS and PDHA1 played a synergistic role in promoting greater glutamine dependence in prostate cancer patients." (PMID 35937995, 2022). "The inhibition of PDHA1 expression in the LnCap human prostate cancer cells led to the “Warburg effect”, resistance to chemotherapy, improved migration, and increased expression of stem cell markers." (PMID 36298586, 2022). "In previous studies, GLS and PDHA1 were found to play a synergistic role in promoting glutamine dependence in prostate cancer patients." (PMID 36588699, 2022). "For example, in PTEN-null prostate cancers, nuclear pyruvate dehydrogenase A1 (PDHA1) is a source of acetyl-CoA for histone H3 K27 acetylation and, as consequence, sustains SREBP1 transcriptional activity." (PMID 34660272, 2021). "The lasso results also showed that five genes (AR, PDHA1, RAN, DPP4 and DAZAP1) were the powerful composed factors of prostate cancer risk prediction model." (PMID 33407865, 2021). "The major mechanism through which PDHA1 knockdown induces prostate cancer suppression is related to abrogation of lipogenesis through a mechanism related to the nuclear localization of PDHA1A." (PMID 31366128, 2019). "Chen and coworkers provided evidence that the impairment of PDC and PDHA1 functions induces tumor suppression in prostate cancers." (PMID 31366128, 2019). "Analysis of prostate cancers showed that both PDHA1 and the PDC activator pyruvate dehydrogenase phosphatase 1 (PDP1) are frequently activated and overexpressed." (PMID 31366128, 2019). "In human prostate cancer tissues, we showed that reduced PDHA1 protein expression predicted worse clinical outcome." (PMID 28076853, 2017). "We also examined PDHA1 protein expression in prostate cancer tissues by immunohistochemistry and observed that reduced PDHA1 protein expression in clinical prostate carcinomas was significantly correlated with poor prognosis." (PMID 28076853, 2017). "Using an immunochemical staining approach, we found about 61.4% (54 of 88 samples) of prostatic cancer samples with reduced PDHA1 protein expression." (PMID 28076853, 2017). "We further immunohistochemically examined the expression of PDHA1 protein in a series of human prostate cancer samples and explored its relationship with pathological characteristics." (PMID 28076853, 2017). "By doing so, the PDHA1 gene in the human prostate cancer cell line LnCap was knockout by TALEN technology, and the glycolysis features and cell stemness in these cells were then studied in comparison to the parental cells." (PMID 28076853, 2017). "Additionally, the aberrant overexpression of PDHA1 in AnoR prostate cancer cells upregulates PPARA and AIFM2 expression through nuclear translocation, collectively suppressing ferroptosis and promoting metastasis." (PMID 41724793, 2026). "Pyruvate dehydrogenase E1 alpha 1 (PDHA1) has been identified as a key regulator in the progression of several malignancies; however, its role in ferroptosis and prostate cancer metastasis remains unclear." (PMID 41724793, 2026).
prostate carcinoma (continued). "In prostate cancer, the narrative unfolds with modified circular RNAs RBM33 (circRBM33) engaging FMR1 (the gene encoding FMRP) to form a complex that preserves pyruvate dehydrogenase E1 subunit alpha 1 (PDHA1) mRNA stability, a critical player in metabolism." (PMID 40271197, 2025). "In addition, it has been reported that the knockdown of PDHA1 expression can inhibit the formation of prostate cancer by inhibiting adipogenesis." (PMID 36117848, 2022). "Inactivation of PDHA1 suppresses tumourigenesis by decreasing Acetyl-CoA levels in prostate cancer." (PMID 35030992, 2022). "Interestingly, whereas the knockdown of Pdha1 in PTEN −/− prostate cancer cells reduced acetylation of histone H3 Lys9 (H3K9ac) at these sites, it had not impact at E2F1 binding sites associated with cell cycle progression genes." (PMID 34660272, 2021). "Collectively, our results show that negative PDHA1 gene expressionis associated with significantly higher cell stemness in prostate cancer cells and reduced protein expression of this gene is associated with shorter clinical outcome in prostate cancers." (PMID 28076853, 2017). "PDHA1 expression was negativelyassociated with the Gleason score of prostate cancers." (PMID 28076853, 2017). "In short, reduced PDHA1 protein expression predicted worse clinical outcome in prostatic cancer." (PMID 28076853, 2017). "All these results show that loss of PDHA1 gene expression significantly upregulates cell stemmness of prostatecancer cells in vitro, which strongly indicates its negative role in the development of prostate cancers." (PMID 28076853, 2017). "PDHA1, a subunit of the pyruvate dehydrogenase complex (PDC), inhibits prostate cancer development in mouse and human xenograft tumor models by affecting lipid biosynthesis." (PMID 36891150, 2023). "Correlation between clinical and pathological variables and PDHA1, PDP1 and PDP2 protein expression in prostate cancer." (PMID 35692804, 2022). "To date, we are the first to knock out PDHA1 gene and successfully establish a PDHA1KO prostate cancer cell line with TALEN technology." (PMID 28076853, 2017). "And by immunhistochemical examination of PDHA1 protein expression in prostate cancer samples, it was revealed that negative PDHA1 protein expression was related with poor clinical outcome in patients with prostate cancer." (PMID 28076853, 2017). "Therefore, to knock out PDHA1 gene and evaluate its roles in prostate cancer cells, LnCap cells was chosen and transfected with the TALEN-PDHA1 plasmids." (PMID 28076853, 2017). "Moreover, prostate cancer cells and human esophageal squamous cancer cells lacking PDHA1 exhibit impaired normal mitochondrial oxidative phosphorylation and a reliance on glycolysis." (PMID 39360273, 2024).